MMP9 (matrix metallopeptidase 9)
Diseases named in the same sentence as MMP9 in open-access papers (continued):
Sharing a sentence is not in itself a finding about the gene and the disease.
tumor (continued). "In general, MMPs have a prominent role in preparing the target tissue to invasion by metastatic cancer cells, and MMP-9 has already been suggested as a biomarker of tumor progression and as a target for anticancer therapy." (PMID 35723387, 2021). "After CCL2 administration, intratumoral MMP9 expression was increased significantly and the survival time was declined dramatically in tumour‐bearing mice." (PMID 34464477, 2021). "For example, MMP2 and MMP9 expression levels were significantly higher in tumour tissues than in normal tissue samples in BC." (PMID 34142438, 2021). "An MMP-9-sensitive peptide sequence was used as a bridge linking cell-penetrating peptide and antifouling peptide sequences to form a tumor-responsive peptide coating." (PMID 33967809, 2021). "MMP-9 plays a key role in cancer development and progression, which is related to tumor metastasis in many types of malignancies." (PMID 33828938, 2021). "NTLS-DCs, the major DC subpopulation in ccRCC, secrete high levels of MMP-9 and tumor necrosis factor-α, which promote tumor cell growth and invasion." (PMID 33746989, 2021). "In DTC with a higher TNM stage, tumor diameter ≥l cm, extrathyroidal extension, or existing lymph metastasis and distant metastases, serum MMP-9 levels were significantly higher than those reported in tumors with early TNM stage and smaller diameter." (PMID 34684168, 2021). "It has been reported that high expression of the S100A11 gene in some tumors can upregulate the expression of MMP-9, thus promoting tumor invasion." (PMID 33763485, 2021). "The important members, including MMP-2 and MMP-9, mainly work to decompose collagen IV in the basement membrane, break the tight and ordered junction between cells, and thereby contributing to tumor growth and metastasis." (PMID 34587874, 2021). "Tumor-associated macrophages (TAMs) have been found to directly result in the degradation of ECM and promote the invasion of the tumor cells by secreting the proteolytic enzymes (MMP-2 and MMP-9) and stromal-associated proteins." (PMID 34722623, 2021). "Research on the relationship between NETs and tumor progression is mostly based on neutrophil proteins (NE, MMP-9, etc.), which are also important components of NETs." (PMID 34327245, 2021). "HY19991 and thioridazine release was triggered by MMP-9 in the tumor microenvironment, and the presence of both an acidic pH and MMP-9 results in PTX release." (PMID 34834387, 2021). "The protein expression level of MMP-2 and MMP-9 was significantly enhanced with the increase of the tumor clinical stages and the metastasis of lymph nodes (N staging)." (PMID 31882379, 2021). "Tumor promotor FAM129A has recently been reported to activate FAK signaling pathway and upregulate MMP2 and MMP9 in tumor tissues." (PMID 34513838, 2021). "The observation that the levels of soluble ALCAM in the uterine aspirate fluids of the patients correlated well with MMP9 staining in tumour tissues indicated the possibility of ALCAM shedding from tumours by the metalloproteinases." (PMID 34680335, 2021). "The expression of matrix metalloproteinase (MMP) 2 and MMP9 is closely related to different types of tumor metastasis." (PMID 34369278, 2021). "On the other hand, Catepsin-f, Mmp-23 and Mmp-9 were among the highest proteases down-regulated in SSMs from tumor-draining lymph nodes." (PMID 34168645, 2021). "This degradation of the extracellular matrix plays an important role in tumor invasion and metastasis, and MMP-9 overexpression has been used by some authors to distinguish among different types of cancer." (PMID 34830096, 2021). "As a heterodimeric transcription factor, NF-κB is composed of p50 and p65 subunits, mediates tumor invasion and metastasis through regulating the expressions of metastasis-associated proteins such as XIAP, MMP-2, MMP-9, cyclinD1, and VEGF." (PMID 35002708, 2021).
tumor (continued). "In head and neck squamous cell carcinoma, tumor cells have been found to instruct BM-MSCs to secrete MMP-9 in a three-dimensional spheroid system." (PMID 33287630, 2021). "Further, matrix metalloproteinases (MMP2, MMP9), which promote tumor invasion and metastasis, are significantly related to a poor tumor prognosis (pancreatic cancer)." (PMID 34381726, 2021). "High expression levels of matrix metalloproteinase‐9 (MMP9) also contributed to tumour vascularization." (PMID 34464477, 2021). "Tumor localized MDSCs rely heavily upon immunosuppression and tissue remodeling through matrix metalloproteases (e.g., Mmp9) to maintain the tumor microenvironment, support angiogenesis, and promote additional tumor metastases." (PMID 34482371, 2021). "Our data suggest that CTX affected MMP-9 secretions, which significantly increased during tumor–CAF crosstalk in the spheroid model." (PMID 34822613, 2021). "Along with the increased expression of MMP9 in individual tumor cells, the combination of these effects will increase the probability of distant metastasis." (PMID 33799999, 2021). "Studies showed that MMP-9 promoted tumor invasion and metastasis by the degradation of gelatin and collagens." (PMID 34336699, 2021). "As MMP-2 and MMP-9 are believed to play a critical role in tumor invasiveness, we determined the expression of these proteinases using Western blotting." (PMID 34934771, 2021). "Among these MMPs, MMP-2 and MMP-9 are zinc-containing gelatinases that have been shown to induce tumor progression by promoting cell invasion and metastasis." (PMID 34769032, 2021). "The overexpression of the MMP-9 enzyme in the ECM of PDAC triggered the drug delivery to the tumor site." (PMID 34503252, 2021). "In metastasis, MMP-9 is considered the most significant protease, and its expression is connected with the growth of local tumor, invasion and metastasis in the majority of the carcinomas." (PMID 34068885, 2021). "MMP9 is a family of related enzymes that destroy the extracellular matrix and are essential factors in facilitating tumor invasion and metastasis." (PMID 36643842, 2021). "Silencing LINC00963 inhibited the activity, proliferation, migration, and invasion of CRC cells, MMP-3 and MMP-9 expressions, moreover, it also blocked cell cycle progression, and inhibited tumor growth and Ki67 expression." (PMID 33536018, 2021). "In particular, MMP-9 regulates extracellular matrix remodelling and deposition in the tumour microenvironment and has a crucial role in cancer development and metastasis." (PMID 34620946, 2021). "MMP-9 expression in tumor tissue (69%) was compared with adjacent gastric mucosa (15%) and a statistically significant difference was found (p-value=0.000)." (PMID 34707964, 2021). "PLD1 induced expression through the RAF/ERK and NF-κB signaling pathways, leads to MMP-9 increased secretion, which promotes tumor invasion and metastasis." (PMID 33718168, 2021). "Tien-Hsien Liquid possesses antimetastasis capacity by decreasing MMP-2, MMP-9 and uPA expression and tumor growth and promoting antiangiogenic effects." (PMID 34659548, 2021). "Secreted proteases, such as MMP-2, MMP-9 promote tumor cell invasion and metastasis by digest the ECM and cell adhesion proteins." (PMID 34094948, 2021). "MMP-9, which is expressed by various cells, can promote cell migration and angiogenesis and is also involved in different tumor pathophysiological processes." (PMID 34869390, 2021). "In this study, tumor volume, several metastatic nodules in the animal model, and the MP-2 and MMP-9 activity in the tumor-bearing site reduced significantly." (PMID 34456716, 2021). "Tumor-associated neutrophils (TANs) release neutrophil elastase (ELA2), collagenase (MMP8) and gelatinase B (MMP9), which contain in their granules." (PMID 33996815, 2021).
tumor (continued). "Compared with either drug alone, the combined treatment of paclitaxel and curcumin can significantly suppress cell proliferation and reduce tumor size, increase cell apoptosis, and reduce the expression of matrix metalloproteinase 9 (MMP9)." (PMID 33912467, 2021). "MMP-9 potentially has been reported to promote angiogenesis and neovascularization within the tumor." (PMID 34835236, 2021). "For example, in pancreatic cancer or Lewis lung cancer, MMP-9 can promote tumor growth and development, invasion, and metastasis." (PMID 34869390, 2021). "CHI3L1 up-regulates pro-inflammatory mediators, CCL2, CXCL2 and MMP-9, all of which contribute to tumor growth and metastasis, and treatment with chitin can significantly reduce these effects." (PMID 33937022, 2021). "Recently, it was shown that the molecule responsible for the immobilization of MMP-9 on the cell surface of fibroblasts in the tumor stroma is LH3." (PMID 33807594, 2021). "Whereas some of the MMPs (e.g., MMP-7) are expressed by the cancer cells, other MMPs (MMP-2 and MMP-9) are synthesized by the tumor stromal cells, including myofibroblasts, fibroblasts, endothelial cells, and inflammatory cells." (PMID 34684168, 2021). "Greater than 80% of detected MMP9 protein expression overlapped with FAM-staining that marks PRISM in the tumor." (PMID 34267368, 2021). "Like MMP2, MMP9 also degrades ECM components of the basement membrane to help facilitate tumor invasion while TIMP1 regulates MMP9 activity." (PMID 33995488, 2021). "The accumulation of neutrophils initiates the tumor angiogenic switch by releasing MMP9 in para-carcinoma from human HCC." (PMID 33763069, 2021). "Various NET components including matrix metalloproteinase 9 (MMP-9), cathepsin G and NE can also stimulate the growth and adhesion of tumor cells." (PMID 34830126, 2021). "TANs are supposed to convert disseminated dormant tumor cells in metastatic cells through the release of neutrophil elastase (NE), matrix metalloproteinase-9 (MMP-9), and oncostatin-M, leading to tumor cell proliferation and invasiveness." (PMID 34885027, 2021). "MMP-9 has been proven to promote the invasion of tumor cells into surrounding tissues, and the metastasis to distant tissues in a variety of tumors." (PMID 34733839, 2021). "The study showed evidence that exosomes released by CTLs contained FasL but led to increased invasive activity from tumour cells in vitro and in vivo through the upregulation of MMP9." (PMID 33815694, 2021). "MMP2 also activates TGF-β to promote epithelial-mesenchymal transformation (EMT), while by releasing vascular endothelial growth factor (VEGF), MMP9 promotes tumor angiogenesis." (PMID 34595119, 2021). "The uptake of MC EVs by tumor cells caused a great increase in MMP-2 and MMP-9 mRNAs and a concomitant significant increase in uPA and uPAR, mainly in the Caco-2 cell line." (PMID 34065529, 2021). "Although the high expression of MMP-9 in clinical studies is considered to be related to tumor invasion, further in vivo and vitro studies are still needed to confirm the role of MMP-9 in OSCC." (PMID 33828938, 2021). "For example, MMP9-cleaved osteopontin fragments contribute to tumor immune escape by inducing the expansion of myeloid-derived suppressor cells." (PMID 33643387, 2021). "MMP9 (extracellular matrix protein) plays a role in invasion, metastasis, promotes the growth of tumor cells in the bone and induces tumor-enhanced bone matrix turnover in PCa." (PMID 34938177, 2021). "MMP-2 and MMP-9 are also known to stimulate tumor angiogenesis and EMT through partial proteolysis of the ECM 53-57." (PMID 34326691, 2021).
tumor (continued). "Downregulation of IL-8 expression levels in stressed mice resulted in lower levels of MMP-2 and MMP-9 in the tumor microenvironment and abolished the effect of stress on tumor metastasis." (PMID 35011682, 2021). "TANs contribute also to the tumor invasion and angiogenesis through the production of MMP9 and vascular endothelial growth factor (VEGF) in the primary and metastatic sites." (PMID 33917620, 2021). "After tumor surgery, 9 months follow-up values of MMP-9 (ng/ml) were decreased by 80% from the value in operation (p<0.05)." (PMID 33735248, 2021). "Ki67 can reflect the proliferative activity of tumor cells and MMP-9 is an indispensable factor for tumor invasion and metastasis." (PMID 34876144, 2021). "At this time point DH82-CDVai neoplasms exhibited a larger peripheral MMP-9 immunopositive area than DH82-UV-CDVai tumors (p = 0.0033) or DH82-medium xenografts (p < 0.0001)." (PMID 33808256, 2021). "The authors found that MMP9 was significantly produced and led to cleavage of protease-activated receptor-1 (PAR1), a G protein-coupled receptor linked to tumor growth." (PMID 34204306, 2021). "In this study, reduced MMP-2 and MMP-9 expression was found in SCARA5-upregulated group which indicated that MMP-2 and MMP-9-mediated degradation of the extracellular matrix was involved in the tumor suppressive function of SCARA5." (PMID 33758617, 2021). "Accordingly, the expression of osteoclast differentiation and function genes Acp5, Ctsk, Mmp9, and Nfatc1 was much higher in the bone of tumor-bearing mice than those in the bone of tumor-free mice." (PMID 33391543, 2021). "MMP9 can take different effects in the process of cell scatter, such as tumor invasion, tumor-induced angiogenesis, immune regulation of tumor microenvironment and the formation of microenvironment before metastasis to promote tumor cell distant metastasis." (PMID 33430865, 2021). "According to related reports, mast cells in the TME can release VEGF to support tumor angiogenesis and degrade extracellular matrix by releasing matrix metalloproteinase-9 (MMP9) to promote metastasis, which is conducive to tumor progression." (PMID 34178625, 2021). "Mice subjected to 30 min of 70% liver ischemia at the time of tumor inoculation had significantly larger tumor number and volume with higher levels of MMP9 in the serum and liver tissue." (PMID 34360975, 2021). "Analysis of mRNA expression has also shown that social isolation-induced stress in mice with liver metastases caused an increased expression of MMP-2, MMP-9, MTI-MMP, and uPA in the tumor and liver tissue compared to the control mice." (PMID 33810259, 2021). "The inhibition of either tumor- or stroma-derived MMP9 has been shown to be sufficient for reducing primary tumor growth." (PMID 34577904, 2021). "Thereafter, western blot was performed to quantify the expression levels of matrix metalloproteinases (MMP)-3 and MMP-9, which were involved in tumor invasion and metastasis." (PMID 33371778, 2021). "Some studies suggested MMP9 played a role in modulateing neovessel remodeling and promoted tumor growth." (PMID 34370778, 2021). "Neutrophils facilitate tumor initiation and proliferation by producing MMP9 and transferring neutrophil elastase to cancer cells." (PMID 34724958, 2021). "The responses of tumor cells to osteocyte-derived CM were characterized by the expression of tumorigenic genes such as Runx2, MMP9, TGFβ, and Snail." (PMID 33802279, 2021). "An analysis of expression level and clinicopathological parameters showed that MMP-9 expression was higher in deeper tumours than superficial tumours, in invasive tumours compared to in non-invasive tumours and high-grade tumours compared to low-grade tumours." (PMID 33923108, 2021). "MMP-9 was reported as a useful marker for tumor metastases and for prognosis in patients including early-stage OSCC, another study correlated MMP-9 expression with tumor invasion and lymph node involvement in oral SCC." (PMID 33735248, 2021).
tumor (continued). "In fact, previous studies have demonstrated that miR-29b-3p directly modulated the expression of MMP-2 and MMP-9 in the tumor microenvironment and thus indirectly regulate epithelial plasticity." (PMID 33740985, 2021). "The 11q22.2 amplification leads to high expression of MMP9 in C2, which can promote tumor cell migration and invasion." (PMID 35223867, 2021). "Neutrophils can even enhance the production of VEGF and the invasion of tumor cells by producing oncostatin M and MMP9." (PMID 33996815, 2021). "uPA is a good candidate because it is able to act on MMP-9 as a substrate and because it plays a major role in tumor progression and metastasis." (PMID 35723387, 2021). "MMP-9 activity from bone marrow-derived CD11b-positive myelomonocytic cells was most relevant for the process of tumor vasculogenesis." (PMID 34055644, 2021). "Meanwhile, down-regulating the expression of MMP2, MMP9 aand MMP13 can reduce tumor cell growth, proliferation and metastasis." (PMID 34820358, 2021). "To confirm our in vitro results on the involvement of ILC2s in the EMT phenomenon, we evaluated by qPCR analysis the expression of murine MMP-9 and N-cadherin in dissociated tumor tissues." (PMID 33953160, 2021). "We found that levels of immunoreactive Ki67 and MMP-9 proteins were diminished in tumours isolated from the CPEB1 group." (PMID 33892791, 2021). "Our results provide compelling evidence that knockdown of MMP-9 has a tumor suppressor function in OSCC, and in particular, MMP-9 exerts a definite inhibitory effect on lymph node metastasis in mice." (PMID 33828938, 2021). "Macrophages secrete MMP9 to induce mesenchymal transition, which supports the tumor-promoting role of macrophage influx." (PMID 33643387, 2021). "The extensive role MMP9 plays in tumor progression allows it to be an excellent target for treatment in gastric adenocarcinoma." (PMID 34503132, 2021). "One clinical study focused on the impact of radiotherapy-induced MMP-9 activation in the healthy tissue surrounding the targeted tumor." (PMID 34055644, 2021). "MMP-9 expression and secretion are primarily driven by MF cells and stromal cell populations in close vicinity to the tumor infiltrates." (PMID 34204115, 2021). "Inherent migration and invasion of many tumor cells is known to be stimulated by MMP-9, which becomes activated by proteolytic cleavage of its externalized precursor, pro-MMP-9." (PMID 33919266, 2021). "In the in vitro experiment, platelets activate tumor cell invasiveness by enhancing metalloproteinase-9 (MMP-9) secretion." (PMID 33996552, 2021). "In myeloid cells, HIF1α was found to induce the differentiation of TAMs to the M2-lineage and promote tumor angiogenesis by HIF1α-dependent matrix metallopeptidase 9 (MMP9)." (PMID 34575959, 2021). "This process also produces matrix metalloproteinase 9 (MMP9), which plays an essential role in tumor initiation." (PMID 34048186, 2021). "As expected, Shannon indices were low (≅0) for tumour subclusters and tissue-specific subclusters (DC_CD207, M_MMP9, OSC_STAR, OSC_LEFTY2), indicating dominance of patient or sampling site (omentum vs non-affected ovary) respectively." (PMID 34238352, 2021). "The tumors growing in IFNβ-deficient mice showed enhanced infiltration of pro-tumor neutrophils expressing the pro-angiogenic factors VEGF and MMP9 and the homing receptor CXCR4 that is usually upregulated in senescent neutrophils." (PMID 34572138, 2021). "With the employment of the Clinical Proteomic Tumor Analysis Consortium (CPTAC), the protein level of MMP9 and Vimentin were positively associated with CD44 in ccRCC tissues." (PMID 34934046, 2021). "We also compared the expression of MMP-9 between tumor tissue and adjacent normal gastric mucosa in 100 cases." (PMID 34707964, 2021).